BTN3A2 (butyrophilin subfamily 3 member A2)
Diseases named in the same sentence as BTN3A2 in open-access papers (continued):
Sharing a sentence is not in itself a finding about the gene and the disease.
tumor (16 papers, 2012 to 2026). "BTN3A2 is abundant in tumor tissues and has been proven to have a negative regulatory effect on natural killer (NK) cells." (PMID 36793048, 2023). "The immune cell markers in LUAD were further studied, after correction of tumor purity, BTN3A2 in LUAD was significantly positively correlated with gene markers in B cells, CD8+ T cells, CD4+ T cells, macrophages, neutrophils, and dendritic cells." (PMID 35873496, 2022). "At present, it has been confirmed that BTN3A1 can kill tumor cells by activating Vγ9Vδ2 T cells, which indicates that it is related to tumor immunity, but little is known about BTN3A2 and BTN3A3." (PMID 36059652, 2022). "First, the “Gene” module analysis revealed that BTN3A2 expression is remarkably positively correlated with invading levels of tumor purity, B cells, dendritic cells, CD8+ T cells, macrophages, neutrophils, and CD4+ T cells in LUAD." (PMID 35873496, 2022). "Nevertheless, our previous study have observed a tumor-promoting role of BTN3A2 that was remotely regulated by rs1679709 at 6p22.1." (PMID 32754194, 2020). "Moreover, BTN3A2 expression is a remarkable positive correlation with invading levels of tumor purity, B cells, neutrophils, CD4+ T cells, dendritic cells, macrophages, and CD8+ T cells in LUAD, and B cells and dendritic cells were linked with a good prognosis of LUAD." (PMID 35873496, 2022). "Surprisingly, MCM3 was positively correlated with the expression of several immune checkpoint molecules, such as HMGB1, BTN3A2, CD276, and VEGFA, in almost all of the tumours." (PMID 38698811, 2024). "In addition, in many tumor models, high expression of BTN3A in tissues and high levels of soluble BTN3A2 and BTN2A in plasma can be used as markers of the efficacy of Vγ9Vδ2 T-cell immunotherapy." (PMID 36793048, 2023). "The BTN3A2 mRNA content was lower in LUAD patients than that in healthy individuals in subgroup analysis on the basis of gender, race, nodal metastasis, smoking, stages, as well as tumor grade." (PMID 35873496, 2022). "BT3 molecules (BTN3A1/BT3.1, BTN3A2/BT3.2 and BTN3A3/BT3.3) are known to be expressed on endothelial cells, in the membrane layer surrounding milk fat-secreting droplet from mammary epithelial cells, on immune cells, and on some tumor cell lines." (PMID 22685580, 2012).
cancer (15 papers, 2015 to 2025). A tumor composed of atypical neoplastic, often pleomorphic cells that invade other tissues. "And the finding demonstrated a strong correlation between elevated levels of immune checkpoints and the SREBF1 in ACC, notably KIR2DL3, IL2RA, CD80, IFNG, BTN3A2, and IL1A, also IFNA1 wass significantly associated with SREBF1 in the majority of cancers." (PMID 40668814, 2025). "Out of them, we selected 4 communities associated with genes CASP8, MAN2C1, BTN3A2 and ARL17A which are all reported in literature as possibly involved in cancer." (PMID 35061909, 2022). "BTN3A2 is also highly associated with CD8+ T cells, Th1 cells and dendritic cells and regulates immune infiltration of cancer through T-cell receptor interactions and nuclear factor signaling pathways." (PMID 36091044, 2022). "Five mutated gene variants that were transferred to the BRCA1-KO fibroblasts (BTN3A2, DDX51, LARP6, AP1G1 and COL18A1) were found to be also present as RNA variants following RNA sequencing of BRCA1-KO fibroblasts after exposure to cancer EVs." (PMID 31200749, 2019). "Studies suggest that BTN3A2 is differentially expressed in a variety of cancers." (PMID 35873496, 2022). "BTN3A2 was recognized as a co-stimulatory molecule from correlation studies in cancer patients." (PMID 26347744, 2015). "The validation of BTN3A2 as a prognostic marker for EOC indicated that BTN3A2 may modulate the infiltration of immune cells and thus the anti-cancer immunity." (PMID 26347744, 2015). "These analyses point out that BTN3A2 may be a possible target for cancer-targeted therapy." (PMID 35873496, 2022). "However, the expression of BTN3A2 is also a marker of good prognosis in many cancer patients." (PMID 34149914, 2021). "For single immune checkpoint gene, the immune stimulator HMGB1 correlated positively with KIF11 in all human cancer types, and TNFSF4, BTN3A1, BTN3A2, and ENTPD1 correlated positively with KIF11 in most human cancer types." (PMID 36742345, 2022). "More importantly, the expression of PIK3R4 in DLBCL was correlated with the immune cell content in the cancer microenvironment, CD8(+) T-cell and neutrophil infiltration and the levels of several immune checkpoint molecules, including BTN3A2, BTN3A1, PRF1, CXCL9, PDCD1, and TIGIT." (PMID 37670973, 2023). "The research on BTN3A2 in cancer is mainly focused on the prognosis of cancer, and there is no report on the treatment of cancer." (PMID 34149914, 2021). "Also of notice, a pronounced number of critical immunomodulators, which were described in an immunogenomic analysis of major TCGA cancer data sets and included PDCD1LG2, BTN3A2, GZMA, BTLA, CD28, ICOS, and IDO1, were contained in the 358 DEG set." (PMID 32603365, 2020).
kidney disease (2 papers, 2023 to 2025). "There were 7 proteins that exclusively associated only with the kidney domain supporting their proximal role in kidney disease (e.g., A4GALT, PCK2, EFNA3, BTN3A2, IDI2, GATM, FAIM)." (PMID 41282674, 2025).
BTN3A2 also shares sentences with these, for which no sentence is quoted: allergic rhinitis (2 papers); Alzheimer disease (2); Anxiety (2); bipolar disorder (2); IgA nephropathy (2); mental disorder (2); systemic lupus erythematosus (2); Adult onset (1); alcohol dependence (1); autism spectrum disorder (1); brain disorder (1); childhood asthma (1); clear cell renal cell carcinoma (1); Graves disease (1); inflammatory bowel disease (1); Intellectual disability (1); manic episodes (1); primary immunodeficiency (1); psoriasis (1); psychosis (1); renal cell carcinoma (1); Stroke (1); viral infections (1).